TPO (thyroid peroxidase)
Diseases named in the same sentence as TPO in open-access papers (continued):
Sharing a sentence is not in itself a finding about the gene and the disease.
amyloidosis (1 paper, 2021). A disorder characterized by the localized or diffuse accumulation of amyloid protein in various anatomic sites. "Antibodies anti-thyroid peroxidase, anti-thyroglobulin, and anti-TSHR were negative and amyloidosis was diagnosed on surgical sample of total thyroidectomy." (PMID 34063105, 2021).
and behavioral problems (1 paper, 2015). "Furthermore Ghassabian and Tiemeier showed that the high titration of anti-thyroid peroxidase antibodies (TPO-Ab) during pregnancy associated with an increased risk of cognitive and behavioral problems in preschool children." (PMID 26494985, 2015).
Aphasia (1 paper, 2023). An acquired language impairment of some or all of the abilities to produce or comprehend speech and to read or write. "Our second aim investigated the association between aphasia severity, age, TPO, education, cognitive reserve, and naming outcomes." (PMID 36827514, 2023).
Arterial thrombosis (1 paper, 2021). The formation of a blood clot inside an artery. "Some studies found an association between TPO-RA and incidence of VTE and arterial thrombosis in patients with chronic liver disease or acquired thrombophilia, such as aPL-positivity or APS." (PMID 34572358, 2021).
autoimmune urticaria (1 paper, 2025). An autoimmune form of urticaria (disease). "While anti-TPO antibody is proposed as a marker for type IIb autoimmune urticaria rather than type I autoallergic urticaria, it did not affect treatment outcomes either in this study." (PMID 40822749, 2025).
bone marrow failure (1 paper, 2024). "Eltrombopag is a thrombopoietin receptor agonist (TPO-RA) able to accelerate megakaryopoiesis, which has been used successfully in patients with bone marrow failure and immune thrombocytopenia (ITP)." (PMID 39274330, 2024).
bone marrow fibrosis (1 paper, 2015). "It should be noted that although the analysis period in previous cost-effectiveness analysis of romiplostim was a lifetime, we did not use this because safety concerns such as the development of bone marrow fibrosis remains regarding the long-term use of TPO-RAs." (PMID 25609557, 2015).
breast tumor (1 paper, 2017). "On the other hand, we have not clearly seen such a tendency on the protein level since the estimated amount of TPO protein measured in five G2 and five G3 tissue samples was similar, irrespectively of the breast tumor stage." (PMID 28575127, 2017).
capillary leak syndrome (1 paper, 2025). A syndrome characterized by leakage of intravascular fluids into the extravascular space. "The capillary leak syndrome resolved as did the transient hypothyroidism that was associated with elevated levels of antibody to thyroid peroxidase." (PMID 41417900, 2025).
chronic liver failure (1 paper, 2021). Liver failure that develops slowly and gradually for some time, possibly for years, often as the result of cirrhosis, or malnutrition. "The expression levels of Gab1, TPO, and c-Mpl mRNA in the liver tissues of rats with chronic liver failure were significantly lower than those observed in the blank group (P < 0.05)." (PMID 33959189, 2021).
cold urticaria (1 paper, 2019). Cold urticaria is a condition that affects the skin. "Patients with negative anti-TPO IgE had a higher frequency of symptomatic dermographism, pressure urticaria, and cold urticaria than those in patients with positive anti-TPO IgE." (PMID 31886301, 2019).
congenital rubella (1 paper, 2023). "Thus, adolescents with congenital rubella were more frequently found to have anti-TPO and anti-TG antibodies and showed a greater proportion of thyroid dysfunction than the control group." (PMID 37293205, 2023).
congenital toxoplasmosis (1 paper, 2025). Toxoplasma infection that is present from birth. "Regarding anti-thyroid antibodies, this study revealed significantly higher TPO-Abs concentrations in the control group compared to the congenital toxoplasmosis group." (PMID 39853582, 2025). "The concentration of TPO-Abs of the control group was higher than that of the congenital toxoplasmosis group with statistically significant difference (P = 0.007)." (PMID 39853582, 2025). "The congenital toxoplasmosis group had lower serum concentrations of TPO-Abs than the control group." (PMID 39853582, 2025).
deafness (1 paper, 2010). An inherited or acquired condition characterized by the complete loss of the ability to hear from one or both ears. "Although patients with TPO defect do not usually have deafness, some cases with both TPO defect and hearing loss, have been reported." (PMID 21274344, 2010). "We suggest that thyroid peroxidase (TPO) gene should be analyzed in pseudo−PDS patients with congenital goitrous hypothyroidism and deafness." (PMID 21274344, 2010). "We also suggest that the TPO gene should be analyzed in pseudo−PDS patients with congenital goitrous hypothyroidism and deafness." (PMID 21274344, 2010).
dermatomyositis (1 paper, 2024). Dermatomyositis (DM) is a type of idiopathic inflammatory myopathy characterized by evocative skin lesions and symmetrical proximal muscle weakness. "These include autoantibodies to Histidyl-tRNA synthetase (Jo-1), Anti-Islet Cell Antigen 512 (IA-2), Tissue Transglutaminase 2 (tTG), Dermatomyositis specific autoantigen Mi-2 (Mi-2), thyroid peroxidase (TPO) and SAE1/SAE2." (PMID 39936155, 2024).
epilepsia partialis continua (1 paper, 2020). "Interestingly, high TPO titers have been linked to epilepsia partialis continua (with motor manifestations)." (PMID 33324338, 2020).
exophthalmos (1 paper, 2021). "Compared with the control group, the overall TAO patients had significantly elevated serum levels of FT3 and thyroid autoantibodies (TPO-Ab, Tg-Ab, and TR-Ab), as well as abnormal ocular signs (increased intraocular pressure and degree of exophthalmos)." (PMID 34774035, 2021).
fibrosis (1 paper, 2025). the formation of excess fibrous connective tissue in an organ or tissue in a reparative or reactive process. "Only a minority of patients experience moderate–severe reticulin and/or collagen fibrosis, which usually reverses upon the discontinuation of TPO-RAs." (PMID 41403445, 2025).
glucose metabolism disorders (1 paper, 2016). "Among the variables included in the model only male gender (OR: 1.98, 95% CI = 1.09–3.60) and positivity for anti-thyroid peroxidase antibodies (OR: 3.37, 95% CI = 1.38–8.24) were significantly associated with glucose metabolism disorders." (PMID 27123460, 2016).
Granuloma (1 paper, 2014). A compact, organized collection of mature mononuclear phagocytes, which may be but is not necessarily accompanied by accessory features such as necrosis. "Presence of Hurthle cell change, giant cells, and granulomas has no statistical correlation with anti-TPO and TSH." (PMID 24808970, 2014).
halo nevus (1 paper, 2015). A benign melanocytic nevus with a halo appearance. "Halo nevus was present in only one patient who was anti-TPO Ab negative." (PMID 25653881, 2015).
hearing loss (1 paper, 2010). "Accordingly, a TPO defect along with hearing impairment might be considered in the etiology of pseudo−PDS." (PMID 21274344, 2010).
hemangiosarcoma (1 paper, 2023). "Though not necessarily relevant to hemangiosarcoma formation, QSAR models were applied to evaluate androgenic activity, estrogenic (ER) activity, and thyroid peroxidase activity of pregabalin with the Leadscope model applier (Instem, Inc.)and ADMET Predictor (SimulationsPlus) platforms." (PMID 38026843, 2023).
hepatitis C (1 paper, 2018). "Different studies have examined anti-thyroid antibodies in different subgroups of patients like in SLE (54.76%), hepatitis C patients (anti-TPO 26.8%), and chronic urticaria patients (anti-TPO 57.4% and anti-TG 42.6%)." (PMID 29850012, 2018).
hereditary thrombocytosis (1 paper, 2024). "For example, hereditary thrombocytosis has been associated with germline GOF mutations in the TPO encoding gene, THPO, that result in increased TPO production due to enhanced mRNA translation, as well as germline MPL GOF and JAK2 GOF mutations." (PMID 38254802, 2024).
Hürthle-cell adenomas (1 paper, 2015). "In Hürthle-cell adenomas low TPO positivity is characteristic both in central and subcapsular follicles; positivity is only outstanding for papillary growth patterns." (PMID 26300979, 2015).
Hypercholesterolemia (1 paper, 2023). An increased concentration of cholesterol in the blood. "One such model is experimental hypercholesterolemia induced by feeding animals a diet with excess cholesterol and simultaneous treatment with a drug interfering with thyroid peroxidase (e.g., mercazolil)." (PMID 37895942, 2023).
hypersomnia (1 paper, 2025). A sleep disorder characterized by excessive sleepiness. "In patients presenting with hypersomnia and elevated anti-TPO antibodies, the diagnosis of SREAT should be promptly considered, particularly in the context of atypical or unclear neuropsychiatric clinical presentation." (PMID 40777071, 2025).
hypertriglyceridemia (1 paper, 2022). A laboratory test result indicating elevated triglyceride concentration in the blood. "Likewise, in SCH patients, hypertriglyceridemia was found in 90.3% of cases of positive anti-TPO antibody sub-group, while in the negative anti-TPO antibody sub-group, hypertriglyceridemia was present in 61.5% of cases (p=0.008)." (PMID 35317033, 2022).
Hyponatremia (1 paper, 2022). An abnormally decreased sodium concentration in the blood. "Recurrent hyponatremia occurred in 2 patients, thyroid peroxidase antibody was elevated in all patients, and rheumatoid factor was positive in 2 patients." (PMID 36582004, 2022).
inflammatory bowel disease (1 paper, 2023). A spectrum of small and large bowel inflammatory diseases of unknown etiology. "ANA, antinuclear antibodies; fT4, free thyroxine; HLA-B27, human leukocyte antigen B27; IBD, inflammatory bowel disease; JIA, juvenile idiopathic arthritis; RF, rheumatoid factor; SD, standard deviation; TG, thyroglobulin; TPO, thyroid peroxidase; TSH, thyroid stimulating hormone." (PMID 37654906, 2023).
influenza (1 paper, 2023). An acute viral infection of the respiratory tract, occurring in isolated cases, in epidemics, or in pandemics; it is caused by serologically different strains of viruses (influenzaviruses) designated A, B, and C, has a 3-day incubation period, and usually lasts for 3 to 10 days. "Molecular mimicry is also unlikely to explain the development of anti-SRP54 and anti-TPO in influenza and SARS-CoV-2 infection, as this mechanism would imply that self-proteins cross-react with proteins from 2 unrelated respiratory viruses." (PMID 36752204, 2023).
Interstitial pneumonitis (1 paper, 2022). "However, Tg Ab and TPO Ab were associated with the occurrence of thyroid irAE and GAD Ab was associated with the occurrence of interstitial pneumonitis." (PMID 35247869, 2022).
intrahepatic cholestasis (1 paper, 2013). A cholestasis characterized by impairment of the bile flow caused by obstruction located in the liver. "The occurance of intrahepatic cholestasis of pregnancy was higher in the TPO-positive group than in the TPO-negative group (P=0.03)." (PMID 23802061, 2013).
invasive carcinoma (1 paper, 2014). A carcinoma that is not confined to the epithelium, and has spread to the surrounding stroma. "In this study, using mice with a thyroid-specific knock-in of oncogenic Braf (LSL-Braf(V600E)/TPO-Cre), the thyroid epithelial cells became transformed and progressed to invasive carcinomas with a very short latency as shown by neoplastic transformation present at birth." (PMID 25076938, 2014).
ischemic cardiomyopathy (1 paper, 2019). Ischemic cardiomyopathy is a cardiomyopathy in which a weakness in the muscle of the heart due to inadequate oxygen delivery to the myocardium with coronary artery disease being the most common cause. "In patients with ischemic cardiomyopathy, the mRNA levels of thyroperoxidase (TPO), a key component of this TH enzymatic machinery, was reduced in association with reduced T3 levels and altered methylation pattern of the TPO gene." (PMID 31555215, 2019).
kidney damage (1 paper, 2025). "Additionally, the markedly higher urine ACR ratio observed in anti TPO positive patients suggests a greater degree of albuminuria, which is a critical marker of kidney damage." (PMID 40937419, 2025).
latent infection (1 paper, 2025). "Moreover, it was proposed that latent infection had a cumulative effect on TPO-Abs concentrations." (PMID 39853582, 2025).
liver dysfunction (1 paper, 2023). "Three RCTs, one exploratory trial, and one expert opinion report were retrieved from the literature search to support the preference for TPO-RAs with low or very low risk of hepatic side effects in ITP patients with concomitant liver dysfunction." (PMID 36826482, 2023). "The experts reached 100% consensus (agree n = 8) for second-line TPO-RAs with very low risk of hepatic side effects (e.g., avatrombopag) as preferable in patients with chronic ITP and concomitant liver dysfunction." (PMID 36826482, 2023).
liver fibrosis (1 paper, 2024). "Therefore, the association between subclinical hypothyroidism and anti-TPO antibodies may reflect a "true" subclinical dysfunction that could influence liver steatosis, or, as previously suggested, these antibodies may impact liver fibrosis by indicating immune aggression." (PMID 39420912, 2024).
liver steatosis (1 paper, 2024). "Importantly, the present study is the first to have shown an association between liver steatosis and autoimmune subclinical hypothyroidism, identified by the presence of anti-TPO antibodies." (PMID 39420912, 2024). "The results of this study strengthen the hypothesis that hepatic steatosis is associated with autoimmune (positive anti-TPO) subclinical hypothyroidism, independently from BMI." (PMID 39420912, 2024).
major depressive episode (1 paper, 2004). "A statistically significant association with anti-TPO+ was found in Anxiety Disorder Not Otherwise Specified (OR = 4.0, CL 95% 1.1–15.5), in Major Depressive Episode (OR = 2.7, CL 95% 1.1–6.7) and Depressive Disorder Not Otherwise Specified (OR = 4.4, S CL 95% 1–19.3)." (PMID 15317653, 2004).
memory loss (1 paper, 2020). "The patient was initially started on anti-epileptics only; however, her headaches and memory loss escalated, further diagnostic workup was pursued, which revealed high anti-thyroid peroxidase antibodies with normal thyroid function tests." (PMID 33409091, 2020).
Menstrual disorder (1 paper, 2024). Category of disorders related to menstruation. "The current study aimed to assess the menstrual disorder and the AMH, TSH, TPO, and prolactin levels in female patients with COVID-19." (PMID 39906086, 2024). "This study aimed to investigate the effect of the COVID-19 virus on menstrual disorders, anti-Mullerian hormone (AMH), thyroid peroxidase (TPO), thyroid stimulating hormone (TSH), and prolactin levels in women with COVID-19 disease." (PMID 39906086, 2024).
metastatic tumors (1 paper, 2025). "In metastatic tumors, significant reductions were observed in DIO1 activity (11-fold), TFF3 gene expression (8-fold), TPO expression (4-fold), and SLC26A7 expression (2.6-fold)." (PMID 40650194, 2025).
myeloproliferative disorder (1 paper, 2012). A clonal hematopoietic stem cell disorder, characterized by proliferation in the bone marrow of one or more of the myeloid (i.e., granulocytic, erythroid, megakaryocytic, and mast cell) lineages. "TPO-induced stimulation of c-Mpl has been implicated in maintaining HSC quiescence and also in myeloproliferative disorders (MPDs) and Gabs play a role in regulating PI-3K and MAPK pathways, in c-Mpl/TPO signaling." (PMID 22216034, 2012).
non-small cell lung carcinoma (1 paper, 2020). A group of at least three distinct histological types of lung cancer, including non-small cell squamous cell carcinoma, adenocarcinoma, and large cell carcinoma. "A recent retrospective analysis of non-small cell lung cancer (NSCLC) patients treated with anti-PD-1 monotherapy demonstrated similar results: pre-treatment anti-Tg and/or anti-TPO antibodies were associated with the development of immune-related hypothyroidism, but not other irAEs39." (PMID 33299547, 2020).
nontoxic goiter (1 paper, 2014). Sporadic enlargement of the thyroid gland that is not associated with changes in thyroid function or malignancy. "A total of ten heterozygous mutations have been identified in the human TPO gene associated with thyroid toxic and nontoxic goiter." (PMID 24482635, 2014). "A total of ten mutations have been identified in the human TPO gene associated with thyroid toxic and nontoxic goiter." (PMID 24482635, 2014). "Sixty-three Arabic patients (16 males and 47 females) with thyroid toxic and nontoxic goiter who attended the endocrinologist in Nuclear Medicine Hospital and Al Yarmok Nuclear Medicine Department in Baghdad, Iraq were examined for thyroid peroxidase (TPO) gene mutations." (PMID 24482635, 2014). "In conclusion, this study identified ten TPO mutations associated with toxic and nontoxic goiter that have not been yet reported in Iraq, and most of them are detected among females (90 %) and adults age between 30 and 50 years old (80 %)." (PMID 24482635, 2014).
osteoarthritis (1 paper, 2023). A noninflammatory degenerative joint disease occurring chiefly in older persons, characterized by degeneration of the articular cartilage, hypertrophy of bone at the margins and changes in the synovial membrane. "This is in line with observations in DPO/TPO treatment where dogs with more advanced osteoarthritis preoperatively are more likely to have an unfavorable clinical outcome after surgery." (PMID 37152693, 2023). "Like DPO/TPO, ACE-X implantation is intended to prevent or delay the progression of osteoarthritis." (PMID 37152693, 2023).
osteoporosis (1 paper, 2021). A condition of reduced bone mass, with decreased cortical thickness and a decrease in the number and size of the trabeculae of cancellous bone (but normal chemical composition), resulting in increased fracture incidence. "Fourth, the results of thyroid function tests, such as TSH, free T4, TPO-Ab and Ag-Ab tests, were not available, and thyroid function may influence the prevalence of osteoporosis." (PMID 33946728, 2021).
ovarian dysfunction (1 paper, 2025). The inability of the ovaries to function. "Our clinical findings indicate that anti-TPO should be regarded as a significant marker of ovarian dysfunction, rather than a benign spectator." (PMID 41303060, 2025).
paraganglioma (1 paper, 2008). A benign or malignant neoplasm arising from paraganglia located along the sympathetic or parasympathetic nerves. "Included in this category also was a TPO-negative paraganglioma of nonthyroid origin and four cases of inoperable undifferentiated carcinoma, all of which were TPO negative." (PMID 18031322, 2008).
periodontitis (1 paper, 2024). An acute or chronic inflammatory process that affects the tissues that surround and support the teeth. "Further adjustment for log-transformed urine iodine levels and thyroid peroxidase antibodies revealed significantly higher odds of periodontitis among subjects in the tertile group with lower TSH than those in the third tertile (OR 1.36)." (PMID 39063437, 2024).
Pleural effusion (1 paper, 2024). The presence of an excessive amount of fluid in the pleural cavity. "The thyroid hormone affects the functioning of nearly all of body organs, and pleural effusion is one of the more severe complications of AITD of note, with very high anti-TPO and anti-TG antibodies, but without TSA." (PMID 39767631, 2024).
prediabetes (1 paper, 2025). "Our study demonstrates an inverse association between central thyroid hormone sensitivity indices and prediabetes, particularly in euthyroid and anti-TPO-negative individuals." (PMID 40600010, 2025).